VEGFA (vascular endothelial growth factor A)
Diseases named in the same sentence as VEGFA in open-access papers (continued):
Sharing a sentence is not in itself a finding about the gene and the disease.
tumor (continued). "Lymphocytes also release cytokines and chemokines, such as IL-16, CCL21, and VEGFA, that attract monocytes, dendritic cells (DCs), and endothelial cells to the tumor core and invasive margin." (PMID 27129159, 2016). "CCL2 has been reported to function as a chemo-attractant, and VEGFA is an important cytokine involved in angiogenesis and tumor growth." (PMID 27541266, 2016). "Intravital imaging of blood vasculature using QDs and fluorescent dextran demonstrated that Tie2hi-expressing TAMs induce transient vascular leakage via vascular endothelial growth factor A (VEGFA) signaling, thereby facilitating tumor cell intravasation." (PMID 27239290, 2016). "miR-590-5p impaired cell proliferation, migration, and tumor angiogenesis mainly by inhibiting NF90/VEGFA axis in vitro and in vivo." (PMID 27735951, 2016). "HIF-1α orchestrates downstream genes essential to the cells' adaption to hypoxia, and HIF-1α is an important transcription inducer for numerous growth factors and cytokines in tumor angiogenesis, most importantly VEGFA." (PMID 27634881, 2016). "In human pancreatic neuroendocrine BON1 cells, RSUME stimulates hypoxia-inducible factor-1α (HIF-1α) and vascular endothelial growth factor-A (VEGF-A), which are key components of tumor neovascularisation." (PMID 27506944, 2016). "VEGFA signalling in B16F10 tumours was examined to understand how leakage was regulated in a tumour context." (PMID 27005951, 2016). "Because angiogenesis plays a critical role in tumor progression, we examined the expression of VEGFA in adenovirus-treated cells in vitro and in vivo." (PMID 27528029, 2016). "Considering that fibroblasts affect the function of cancer cells via paracrine, we suggested that FOXO3a functions as a tumor suppressor in fibroblasts and cancer cell co-culture through inhibition of VEGFA expression." (PMID 27541266, 2016). "The predicted UPR activity of VEGFA in LLC tumors was verified experimentally by the significant reduction in LLC tumor microvessel density following CPA/6d treatment." (PMID 27515027, 2016). "In this way VEGFA primarily induces endothelial cell proliferation and migration, promoting the aberrant angiogenesis that supports tumor growth and tumor metastasis." (PMID 26920352, 2016). "Since Janus kinases (JAKs) mediate STAT3 activation in tumor angiogenesis, we first tested the effect of VEGFA on Jak1 and Jak2 tyrosine phosphorylation in HRMVECs." (PMID 27210483, 2016). "So in order to decrease tumor angiogenesis and its motion, many researches tried different method to inhibit the expression of VEGFA." (PMID 26901069, 2016). "Upon expression VEGFA is released into the environment by the tumor cells and binds to its corresponding receptors mainly on endothelial cells." (PMID 26920352, 2016). "Tumor cell-produced VEGFA can contribute to tumor cell progression and metastasis through stimulating tumor cell survival, migration and invasion." (PMID 27015364, 2016). "VEGFA is a key regulator of angiogenesis and plays an important role in regulation of tumor metastasis." (PMID 27777493, 2016). "Although there is evidence that bevacizumab reduces tumor edema, angiogenesis, and disease burden, the use of this agent as well as other VEGFA/VEGFR2-targeting drugs has been followed by adaptive tumor responses in preclinical models and clinical settings." (PMID 26910374, 2016). "Tumor angiogenesis: Tumor angiogenesis is a key step in cancer development and progression, driven by pro-angiogenic growth factors such as vascular endothelial growth factor-A (VEGF-A)." (PMID 27509527, 2016). "In ovarian cancer, hypoxia induces angiogenesis in humans and mice, where CD4+, CD25+ and tumour-infiltrating regulatory T cells secrete high quantities of VEGFA and promote the dissemination of endothelial cells, both ‘in vitro’ and ‘in vivo’." (PMID 26913068, 2016).
tumor (continued). "In an ovarian tumour transplanted in a mouse, the depletion of tumour-infiltrating regulatory T cells correlates with a reduction in VEGFA, supporting the role of tumour-infiltrating regulatory T cells in angiogenesis in this type of tumour." (PMID 26913068, 2016). "It has been demonstrated that basigin-2 contributes significantly to tumor growth, metastasis and angiogenesis through stimulating the production of hyaluronan, multiple matrix metalloproteinases (MMPs) and vascular endothelial growth factor A (VEGF-A)." (PMID 27057625, 2016). "Angiogenesis is triggered by vascular endothelial growth factor (VEGFA), which is produced in the tumor." (PMID 27583442, 2016). "Vascular endothelial growth factor A (VEGF-A) is a key player in the process of tumor angiogenesis, and the VEGF pathway has therefore been an important focus for anti-cancer drug development." (PMID 26789111, 2016). "Vascular endothelial growth factor A (VEGFA) plays an important role in tumour angiogenesis and its angiogenic action is mainly mediated through its VEGF receptor 2 (VEGFR-2)." (PMID 25859636, 2015). "It was found that over-expression of VEGFA in cervical cell lines increased the tumor growth by activating PI3K/Akt, and subsequently its downstream to the mTor signaling pathway." (PMID 26308848, 2015). "VEGFA has been identified as the predominant tumour angiogenesis factor in the majority of human cancers, including those of the breast, colon, lung and prostate, and thus is a major target for cancer treatment and drug development." (PMID 26404389, 2015). "Since VEGFA expression has been correlated with tumour invasiveness, and the presence of vaso-invasion negatively affects clinical outcome, blocking both IL-6 and VEGFA has the potential to counteract both tumour growth and invasion." (PMID 25889974, 2015). "Tumour angiogenesis is mainly driven by vascular endothelial growth factor alpha (VEGFA) and platelet-derived growth factor alpha (PDGFA) in response to certain stimuli derived from the tumour cells directly or from the surrounding microenvironment." (PMID 25734337, 2015). "The underlying mechanism appeared to be related to inhibition of cell cycle and reduction of the tumor promoting cytokines vascular endothelial growth factor-A and TGF-β1." (PMID 25996501, 2015). "Anti-angiogenic therapies (AAT) were used as an adjuvant mainly against vascular endothelial growth factor and its receptors (VEGF-VEGFRs) to normalize tumor vasculatures in GBM patients." (PMID 27042399, 2015). "Hypoxia, which is one of the main characteristics of the tumour microenvironment, induces VEGFA expression by increasing transcription, translation, and mRNA stabilisation." (PMID 26404389, 2015). "The invasiveness occurred through MMP2 and MMP3, while inhibition of VEGFA decreased the tumor growth." (PMID 26308848, 2015). "In vitro analysis of the necrotic tumor-inducing cell lines revealed that these cells released a significant amount of vascular endothelial growth factor A (VEGFA)." (PMID 26452217, 2015). "Tumours with lymphatic spread showed higher gene expression rates of VEGFA, EFNB2 and ANGPT2 in moderately differentiated tumours and of VEGFA and EFNB2 in small tumours, respectively." (PMID 26044849, 2015). "The eIF family proteins are also key regulators of tumor angiogenesis that function by upregulating angiogenic factors such as VEGFA and HIF1α." (PMID 25993439, 2015). "Tumor hypoxia induced 4E-BP1, decreases cap-dependent translation and activates cap-independent translation of mRNAs encoding HIF1α and VEGFA, which contributes to cell survival and angiogenesis." (PMID 26204490, 2015). "Inhibition of VEGFA production in tumor cells has previously been reported to induce apoptosis in-vitro and a reduction in levels of VEGFA also suggests a potential anti-angiogenic effect of SINE compound treatment in vivo." (PMID 26573568, 2015).
tumor (continued). "Tumor tissue sections were prepared, and immunohistochemistry was performed with EpCAM, Ki67, and VEGFA antibodies." (PMID 26356670, 2015). "For example, VEGFA promotes angiogenesis and, consequently, nourishment and proliferation of tumor masses." (PMID 26089392, 2015). "VEGFA was found to be among the predicted high confidence targets, and was chosen for further validation due to its well-known importance in tumor angiogenesis." (PMID 26336827, 2015). "In endothelial cells, upregulation of miR-132 positively controls proliferation, angiogenesis and tumour growth in response to vascular endothelial growth factor A (VEGF-A) by suppressing p120RasGap (RASA1)." (PMID 26475020, 2015). "It has been shown that VEGFA activity is critical for tumor growth and angiogenesis and that blocking this signal transduction pathway can inhibit tumor progression." (PMID 26274316, 2015). "We also found that bevacizumab induces VEGFA expression in tumor cells, suggesting a biologic rationale for extending bevacizumab treatment beyond first progression." (PMID 26372896, 2015). "One of the important angiogenic factors is vascular endothelial growth factor-A (VEGF-A) produced by tumor cells." (PMID 25909226, 2015). "The only significant increase in gene expression levels was noted for VEGFA, whose expression was up-regulated by 10.7% in the host cells on Day 3 versus Day 8 (*P = 0.044, N = 5–7) and by 11.7% in the tumour cells between days 3 and 8 (*P = 0.052, N = 2–3)." (PMID 24450440, 2014). "Taken together, CXCR7 promotes tumor development by enhancing the expression and secretion of the proangiogenic factors VEGFA, which are likely to regulate tumor angiogenesis." (PMID 25341042, 2014). "On the other hand, all antibody-based VEGFA-pathway inhibitors and high-dose(50 mg/kg) OXi4503 had beneficial effects on both the primary tumours and post-surgicalmetastases." (PMID 25394647, 2014). "These high-throughput arrays revealed for the first time that enhanced synthesis and secretion of cytokines like VEGFA and galectin-3 participate in the regulation of tumor angiogenesis and contribute to CXCR7-mediated metastatic phenotype." (PMID 25341042, 2014). "The mismatch between tumor growth and vascular supply leads to hypoxia and the up-regulation of multiple cytokines, such as vascular endothelial growth factor A (VEGF-A), which increases microvascular permeability and plays a dominant role in angiogenesis." (PMID 24466160, 2014). "Previous studies also confirm the relationship between tumor vascularization and VEGFA overexpression." (PMID 24777200, 2014). "VEGFA expression was reported to be involved in the HN-Eso-1 cell autocrine system and to have a protective effect against anti-tumor agents." (PMID 24604236, 2014). "Vascular endothelial growth factor-A (VEGF) plays a fundamental role in tumour growth, vascularisation and metastasis and exists as multiple isoforms derived by alternative splicing of the VEGF gene." (PMID 25119572, 2014). "TAM originate from circulating monocytes which are recruited to the tumor site and programmed by tumor-derived factors such as colony-stimulating factor-1 (CSF-1), vascular endothelial growth factor A (VEGF-A) and CC chemokine ligand 2 (CCL2)." (PMID 24634660, 2014). "EGFR and VEGFA/B/C expression in human disease pathways play an important regulatory role in tumor angiogenesis, invasion and metastasis." (PMID 23943374, 2014). "Next, we examined the association of the VEGF gene with tumor subtypes and DMFS and noted a significant association between high VEGFA expression and worse DMFS in HER2+ patients." (PMID 25280532, 2014). "TAMs promote a microenvironment that supports tumor growth and metastasis through the production of growth and angiogenic factors, including VEGFA." (PMID 24932473, 2014). "Tumor-associated macrophages (TAM) sense hypoxia in avascular areas of tumors, and react by production of angiogenic factors such as VEGFA." (PMID 24634660, 2014).
tumor (continued). "Taken together, our results strongly suggest existence of human tumor endothelial cells in all tumor types tested and of both stromal and tumoral autocrine VEGFA-VEGFR1/2 signalings." (PMID 24625025, 2014). "Secretion of pro-angiogenic mediators by tumor cells, most notably vascular endothelial growth factor A (VEGF-A), promotes endothelial cell migration and proliferation." (PMID 24375628, 2014). "The average levels of vascular endothelial growth factor A (VEGFA) in both the tumor tissues and serum of subcutaneous implantation models bearing CXCR7-transfectant HepG2 were significantly higher than that of control (P<0.05)." (PMID 25341042, 2014). "By the time sunitinib has lost its potency, VEGFA expression is still elevated, leading to hyperactivation of VEGFRs, resulting in hyperproliferation of endothelial cells, hence explaining the tumor relapse after sunitinib treatment." (PMID 23720233, 2013). "Bevacizumab (Avastin) is an antiangiogenic humanized monoclonal antibody against vascular endothelial growth factor A (VEGF-A), which by normalization of tumor vasculature can improve drug delivery to the tumor." (PMID 25032013, 2013). "The well-established role of vascular endothelial growth factor-a (VEGF) in tumor angiogenesis has led to the development of therapeutic strategies that selectively target the VEGF pathway." (PMID 23651517, 2013). "Here we demonstrated that miR-26a is associated with decreased tumor angiogenesis in HCC, at least partly through decreasing VEGFA expression by directly inhibiting PIK3C2α." (PMID 24194905, 2013). "VEGFA is a key regulator of blood vessel formation and plays an important role in angiogenesis, which contributes to tumor development and progression." (PMID 23536895, 2013). "These CCR10+ Tregs contributed to tumor progression by secreting vascular endothelial growth factor A (VEGF-A), thereby promoting angiogenesis." (PMID 23874342, 2013). "This process, called tumour angiogenesis, is mediated primarily by vascular endothelial growth factor A (VEGF-A)." (PMID 24416596, 2013). "Tumor cells secret VEGFA to induce vasculature to develop, allowing a sufficient supply of oxygen and nutrients." (PMID 23536895, 2013). "Taken together with the results of increased metastatic potential of FETα/DNRII cells in the orthotopic model, our studies suggest that TGF-beta signaling suppresses VEGFA-mediated angiogenesis and tumor progression." (PMID 23536895, 2013). "It is clear that the angiogenesis factor VEGFA is involved in tumor growth and spread, and promotes angiogenesis by binding VEGFR1 and VEGFR2." (PMID 24349832, 2013). "Analysis of GBM tumor tissues suggests that increased ligand to receptor ratio of VEGFA to VEGFR2 correlates negatively with survival; however, this correlation was not statistically significant." (PMID 24287492, 2013). "During the early stages of tumor growth, hypoxia upregulates VEGFA and VEGFR1 expression, making these proteins attractive as drug targets." (PMID 23395639, 2013). "Vascular endothelial growth factor-A (VEGF-A) is the primary activator of tumour angiogenesis and functions by binding to VEGF-Receptor 2 (VEGF-R2) and is often required for tumour growth beyond 2–3 mm." (PMID 23914254, 2013). "VEGFA and other angiogenic factors expressed under hypoxic conditions have been proposed as important tumor prediction factors in UCC." (PMID 22895562, 2012). "A humanized monoclonal antibody targeting VEGFA, Bevacizumab, has been approved for the treatment of several tumour types, including EOC." (PMID 23029477, 2012). "Invasive SCC also expresses increased levels of VEGFA, particularly in the leading front of the tumor, which is an intuitive site for the induction of angiogenesis." (PMID 23166713, 2012). "VEGF, whose most important member is VEGFA, is the most potent angiogenic factor and plays a key role in tumor associated angiogenesis and hyper-permeability." (PMID 22615958, 2012).
tumor (continued). "Even more interesting, a positive correlation between miR-126 and VEGFA expression was observed, which suggests a possible positive regulatory role of miR-126 in tumor angiogenesis." (PMID 23029111, 2012). "Vascular endothelial growth factor-A (hereafter referred to as VEGF) is a key regulator of angiogenesis, a process fundamental to the growth and metastasis of tumours." (PMID 22567098, 2012). "VEGFA, a major mediator of tumour angiogenesis, was significantly upregulated in MD/PD SC, and a high expression was associated with a short progression-free survival." (PMID 23029477, 2012). "This study also demonstrated the correlation between the expression of VEGFA and its receptors within tumor cells, supporting an autocrine and paracrine function of VEGFA." (PMID 23203097, 2012). "VEGFA has been identified as the predominant tumor angiogenesis factor in the majority of human cancers, including those of the breast, colon, lung and prostate." (PMID 23166713, 2012). "In a study of 50 invasive ductal carcinomas, expressions of VEGFA protein and mRNA were correlated with tumor size, lymph node metastasis and TNM staging." (PMID 23203097, 2012). "Vascular endothelial growth factor-A (VEGF-A) is considered to be the most important and potent pro-angiogenic factor involved in tumor growth." (PMID 22485142, 2012). "Tumour cells also release soluble mediators such as VEGF-A (vascular endothelial growth factor-A), TGF-β and TNF-α that act on myeloid and endothelial cells and induce the expression of non-classical chemokines such as the S100 chemokine." (PMID 23905066, 2012). "Specific SNPs in the VEGFA gene resulted able to determine response to chemotherapy through modulation of tumour blood vessels structure and function." (PMID 22808003, 2012). "It is also clear that Notch plays an important role in angiogenesis driven by Vascular Endothelial Growth Factor A (VEGF-A)—a process instrumental for tumor growth and metastasis." (PMID 21533193, 2011). "Our aim was to investigate the role of VEGFA in promoting tumour growth through interaction with its environment." (PMID 22045186, 2011). "As expected, VEGFA was significantly higher expressed in the VEGFA165 tumours compared with control tumours (P<1 × 10−5)." (PMID 22045186, 2011). "Together these data show that stroma-derived (i.e. mouse-derived) cytokines are regulated in tumours overexpressing VEGFA, suggesting that VEGFA exerts its effect on tumour growth via a paracrine loop." (PMID 22045186, 2011). "Noticeably, there were also positive correlations between tumor weight and VEGFA levels for the two primary tumor lines." (PMID 21955618, 2011). "Our data revealed that, in response to VEGFA expression by the tumour cells, these host-derived cytokines were upregulated." (PMID 22045186, 2011). "The EFEMP1 suppression of tumor onset time was nearly restored by ectopic VEGFA expression; however, overall tumor growth rate remained suppressed." (PMID 21955618, 2011). "Over-expression of EFEMP1 eliminated tumor development and suppressed angiogenesis, cell proliferation, and VEGFA expression, while the converse was true with knock-down of endogenous EFEMP1 expression." (PMID 21955618, 2011). "We demonstrated that tumour-derived VEGFA resulted in enhanced tumour cell proliferation possibly by a paracrine inhibition of TGF-β signalling within the tumour." (PMID 22045186, 2011). "The tumor onset time (time when the tumor becomes measurable) for all three VEGFA-transfectants was 17 days, close to that of the original U251HF at day 12, whereas the tumor onset time of the lacZ-transfectant is 40 days after implantation." (PMID 21955618, 2011). "At day 23 after implantation, the average tumor weight from VEGFA-transfected EFEMP1c6 was 24-27% of U251HF." (PMID 21955618, 2011). "One predominant factor that stimulates tumor angiogenesis is vascular endothelial growth factor A (VEGF)." (PMID 20628530, 2010).